FAM138E (family with sequence similarity 138 member E)
Synonyms: F379
Gene: Long non-coding RNA gene on chromosome 15 (101,953,420 to 101,956,412, forward strand). Ensembl gene ENSG00000248893.
Diseases named in the same sentence as FAM138E in open-access papers:
FAM138E is named in the same sentence as 2 diseases in open-access papers, as found by Europe PMC text mining. Sharing a sentence is not in itself a finding about the gene and the disease. The quoted sentences say what the papers report.
gynecologic cancers (1 paper, 2020). "The recurrent CNV events shared by gynecologic cancers are predicted to cause amplifications of retinal proteins FAM138D and FAM138E, and deletions of genes associated with IFN-α/β signaling, which can be viewed as a strategy of immune evasion." (PMID 33194730, 2020).
FAM138E also shares sentences with these, for which no sentence is quoted: tumor (1 paper).